OCLN (occludin)
Diseases named in the same sentence as OCLN in open-access papers (continued):
Sharing a sentence is not in itself a finding about the gene and the disease.
hepatoma (18 papers, 2011 to 2025). "HCV was adapted via passaging an HCV infectious virus clone several times in human hepatoma cells, mouse liver cells, and eventually primary mouse hepatocytes deficient in innate immunity and ectopically expressing human occludin and human CD81." (PMID 40242309, 2025). "Therefore, we overexpressed wt or mutated forms of CLDN6 and OCLN in hepatoma Huh-7 cells that endogenously express CLDN1, -6 and OCLN proteins." (PMID 26561856, 2015). "Thus, it is tempting to speculate that the ADRP-occludin axis may provide a working hypothesis for the increased risk of hepatocellular carcinoma in patients with hepatitis C and steatosis." (PMID 26731658, 2016). "Another study described significantly lower levels of occludin in metastasis than in primary hepatocellular carcinoma." (PMID 40173205, 2025). "In this study, we characterized the functions of the late host entry factors: epidermal growth factor receptor (EGFR), claudin-1 (CLDN1), and occludin (OCLN) during HCV entry into polarized hepatoma spheroids." (PMID 38157366, 2023). "To investigate the role of TACSTD2 in regulating CLDN1 and OCLN distribution in hepatoma cells, we performed TACSTD2 gene silencing using a pool of 4 siRNA (siTACSTD2) and examined the distribution of the two HCV-entry cofactors by confocal microscopy." (PMID 29538454, 2018). "This protein is involved in the maintenance of the proper cellular localization of the two major HCV-entry cofactors, CLDN1 and OCLN, within hepatoma cells and primary human hepatocytes." (PMID 29538454, 2018). "Immunoblot analysis of all four HCV entry factors (CLDN1, OCLN, SRBI, and CD81) in HFLC showed levels of expression comparable to those of the HCV-susceptible hepatoma Huh-7.5." (PMID 22144107, 2011). "As reported for claudins, occludin may be over- or under-expressed during tumor progression, with evidence of the former in hepatocellular carcinoma and the latter in endometrial carcinoma." (PMID 38141113, 2024). "Additionally, HCV infection altered TJ function with changes in localization of occludin and claudin-1 in hepatoma Huh7 cells, with occludin being required for HCV pseudotyped particles entry." (PMID 35328419, 2022). "The results of our gene silencing experiments demonstrated that TACSTD2 is involved in the maintenance of the proper cellular localization of two TJ proteins that are essential for HCV entry, CLDN1 and OCLN, both in hepatoma cells and in primary human hepatocytes." (PMID 29538454, 2018). "TACSTD2 gene silencing disrupts the typical linear distribution of CLDN1 and OCLN along the cellular membrane in both hepatoma cells and primary human hepatocytes, recapitulating the pattern observed in vivo in primary HCC tissue." (PMID 29538454, 2018). "Finally, we must mention the fact that the expression of both ADRP and occludin correlates with the degree of steatosis in patients with non-alcoholic fatty liver disease, and that occludin is increased also in hepatocellular carcinoma tissue compared to normal livers." (PMID 26731658, 2016). "In this paper, we evaluate the roles of three entry factors in polarized hepatoma spheroids: epidermal growth factor receptor (EGFR) and tight junction proteins claudin-1 (CLDN1) and occludin (OCLN)." (PMID 38157366, 2023). "Strikingly, the abnormal localization of CLDN1 and OCLN that we documented following TACSTD2 silencing both in hepatoma cell lines and in primary human hepatocytes was analogous to that observed in tumor tissue of patients with HCV-associated HCC." (PMID 29538454, 2018). "In the present study, we documented that TACSTD2 is phosphorylated also in hepatoma cells and showed that the phosphorylated form of TACSTD2 interacts with CLDN1 and OCLN." (PMID 29538454, 2018). "The roles of tight junction proteins CLDN1 and OCLN had not been studied in the context of polarized hepatoma spheroids." (PMID 38157366, 2023).
hepatoma (continued). "While study in hepatocellular carcinoma, urothelial carcinoma show occludin expression without clinic-pathological impact." (PMID 27398181, 2016). "Consistent with the observation that these cell lines already express the necessary levels of the four HCV entry factors, over-expression of CD81, SR-BI, CLDN1 or OCLN individually or in combination did not significantly increase HCVpp or HCVcc entry in any of the hepatoma cell lines." (PMID 22273112, 2012).
colorectal cancer (16 papers, 2016 to 2025). A primary or metastatic malignant neoplasm that affects the colon or rectum. "Occludin mRNA expression was a significant predictor of RFS in the whole group of colorectal cancers, with patients with suppressed expression displaying worse RFS." (PMID 37998722, 2023). "In IBD and colorectal cancer, the expression levels of occludin and ZO-1 are reduced, but the expression level of claudin-2 is increased." (PMID 35865942, 2022). "Consistently, the reduced levels of ZO-1 and occludin in colorectal cancer mice were significantly attenuated by BL supplementation." (PMID 34684488, 2021). "Western blot (WB) results further confirmed that the expression levels of epithelial markers (E-cadherin and occludin) were upregulated after the knockdown of COMP by colorectal cancer cells." (PMID 32754278, 2020). "Interestingly, a recent report showed that BECLIN-1 knockdown results in OCCLUDIN levels increasing on membranes in colorectal cancer cells (and decreasing when autophagy is induced using Tat-Beclin1 peptide)." (PMID 40395982, 2025). "Moreover, phytoestrogens such as soya genistein have been observed to increase occludin, zo-1, e-cadherin and β-catenin mRNA and protein expressions in the ApcMin/+ mouse model of colorectal cancer and in Caco-2 cells." (PMID 27907206, 2016). "Moreover, the depletion of RBM47 led to the downregulation of epithelial-associated genes including OCLN, CDH1, TJP1, and CLDN1 with a concomitant enhancement in cell migration, mesenchymal markers, invasion and metastasis in colorectal cancer, which was consistent with our report." (PMID 35831298, 2022). "Colorectal cancer cell derived exosomes miR-25-3p targeted KLF2 and KLF4 to regulate the expression of VEGFR2, ZO-1, occludin and Claudin5, increase vascular permeability and promote angiogenesis." (PMID 35173549, 2022). "By combining bioimaging and genetic tools with artificial intelligence algorithms applied to colorectal cancer cell, we found that the APC-dependent actin pool contributes to sustaining levels of F-actin, as well as E-cadherin and occludin protein levels at cell junctions." (PMID 37128612, 2023). "Previously, studies showed that in rat intestinal epithelium-derived line, IEC-6, caco-2 and colorectal carcinoma cells, downregulation of CDX2 by the MEK/ERK signaling pathway may decrease the protein expression levels of claudin-1, occludin and ZO-1." (PMID 30004434, 2018).
asthma (14 papers, 2014 to 2025). "The biopsy results of bronchial epithelial cells in asthma patients showed that the transcriptional loss of ZO-1 and Occludin caused the increased permeability of the airway epithelial barrier." (PMID 39201796, 2024). "House dust mite (HDM) extract, one of the major causes of asthma (and asthma exacerbations) in children, contains proteases that are known to cleave junctional proteins including occludin and ZO-1, directly participating in barrier dysfunction." (PMID 38529406, 2024). "We studied expression of innervation markers: ubiquitin carboxy-terminal hydrolase L1 (UCHL1/PGP9.5) and occludin (OCLN) as well as genes reported to be associated with asthma: periostin (POSTN), galectin-3 (LGAL3), secretory leukocyte protease inhibitor (SLPI), IL-4, IL-5, IL-13, IL-17." (PMID 35534846, 2022). "Reduction in OCLN levels has been associated with impaired barrier function in asthma patients." (PMID 35534846, 2022). "Our observations of lower expression of key junctional proteins, claudin-1, occludin, ZO-1, and e-cadherin, corroborate our earlier findings in children with mild asthma and suggest the airway epithelium in children with acute wheeze is inherently impaired." (PMID 40791985, 2025). "In these upper airway diseases and asthma, the airway epithelium becomes dysfunctional due to the impaired formation of tight junctions through E-cadherin and occludin." (PMID 40558541, 2025). "To characterize the impact of necroptosis on cellular junction molecules in asthma, we next analyzed the expression levels of occludin and ZO-1 in TL1A- and OVA-challenged mice." (PMID 38987753, 2024). "Epithelial AJCs, both witnessing and driving apico-basal polarization, are altered in asthma, with biopsies from asthma patients displaying abnormal patchy staining for tight junctions (TJ) proteins OCLN and ZO-1." (PMID 34248677, 2021). "Bronchial epithelium from patients with asthma has been shown to exhibit an irregular ZO-1 and occludin staining pattern and reduced barrier function that is further compromised by exposure to the Th2 cytokines IL-4 and IL-1334,35." (PMID 33790367, 2021). "Additionally, VDR expression was lower in patients with comorbid asthma (p = 0.036), and significantly reduced levels of OCLN (p = 0.006), CTNNB1 (p = 0.004), and FLG2 (p = 0.046) were observed in patients with total serum IgE ≥ 100 IU/mL." (PMID 40649943, 2025). "Moreover, MMP-9 alters the localization of tight junction components, such as claudin-1, occludin, and ZO-1, adversely affecting barrier function and eventually directly damaging respiratory epithelium in asthma." (PMID 24533168, 2014). "Similar to our data in asthma, a recent study indicates that in a piglet model of intestinal injury, pretreatment with Nec-1 inhibited LPS-induced necroptosis, improved the reduced expression of jejunal tight junction proteins claudin-1 and occludin protein, and ameliorated barrier function." (PMID 38987753, 2024). "Analysis of tight‐junction gene sets revealed the reduced expression of a whole cluster of genes such as OCLN, CLDN3, CLDN4, NRAS, HCLS1, MYH10 in virus‐infected cells from patients with asthma in comparison to the controls." (PMID 39466641, 2025). "Given that this experimental model of asthma exacerbation in menopause is novel and little explored, especially in the context of the gut−;lung axis, we explored the expression of genes related to the colon barrier, such as MUC 1, MUC 2, and OCLN, in this novel model." (PMID 40292217, 2025).
brain edema (14 papers, 2018 to 2025). Increased intracellular or extracellular fluid in brain tissue. "In the present study, alterations of cellular ATP generation and tight junction associated proteins, i.e., occludin and ZO-1, were further explored by using this mouse model of brain edema." (PMID 29410610, 2018). "The serum occludin level is associated with cerebral edema and could potentially be used as a biomarker for perioperative cerebral edema." (PMID 32884584, 2020). "Interestingly, we found a positive correlation between the peritumoral or pericavity brain edema and the level of serum occludin, with a higher occludin level associated with more severe brain edema." (PMID 32884584, 2020). "Taken together, our data suggest that calcium overload and downregulated expression of tight junction associated proteins, such as occludin and ZO-1 might be the primary events occurring in the early phase of brain edema induced by subacute poisoning of 1,2-DCE." (PMID 29410610, 2018). "At an optimal cutoff of 3.015 ng/mL, the preoperative serum occludin level discriminated between mild and severe preoperative brain edema with a sensitivity of 90.48% and specificity of 84.62%." (PMID 32884584, 2020). "At an optimal cutoff value of 3.015 ng/mL, the preoperative serum occludin level discriminated between mild and severe preoperative brain edema with a high sensitivity (90.48%) and specificity (84.62%)." (PMID 32884584, 2020). "We wanted to know if miR-7-5p is also associated with MMP-9, ZO-1, occludin, TNF-α, IL-6, NLR, and CRP and if it jointly affects brain edema." (PMID 33392188, 2020). "At an optimal cutoff value of 3.033 ng/mL, the postoperative serum occludin level also distinguished between mild and severe postoperative brain edema with a high sensitivity (97.30%), although the specificity was somewhat lower (55.56%)." (PMID 32884584, 2020). "The serum occludin level correlated positively with the degree of brain edema preoperatively (r = 0.78, P < 0.001) and postoperatively (r = 0.59, P < 0.001)." (PMID 32884584, 2020). "The objective is to explore the effectiveness of serum occludin on predicting the extent of perioperative brain edema and outcome in patients with brain tumors." (PMID 32884584, 2020). "Taken together, the findings of the ROC curve analysis suggest that the serum occludin level has the potential to be a novel biomarker for perioperative brain edema in patients with brain tumors." (PMID 32884584, 2020). "At an optimal cutoff value of 3.033 ng/mL, the postoperative serum occludin level distinguished between mild and severe postoperative brain edema with a sensitivity of 97.30% and specificity of 55.56%." (PMID 32884584, 2020). "In our previous study, it was reported that the expression levels of both ZO-1 and occludin decreased markedly at the early phase of brain edema, induced by subacute poisoning with 1,2-DCE, consistent with present findings." (PMID 30524279, 2018). "Importantly, this study revealed a relationship between the serum level of occludin and the severity of brain edema in patients with brain tumors." (PMID 32884584, 2020). "Our study found that the serum occludin level correlated well with the grade of brain edema, suggesting that damage to occludin in the BBB may be a common molecular mechanism underlying the development of brain edema in patients with brain tumors." (PMID 32884584, 2020). "Furthermore, we demonstrated that the serum occludin level correlated well with the degree of brain edema and could be used to predict the severity of perioperative brain edema in patients with brain tumors." (PMID 32884584, 2020). "The breakdown of TJ proteins, such as ZO-1 and occludin, helps the BBB breakdown and the development of cerebral edema." (PMID 36293548, 2022).
brain edema (continued). "Findings from this study demonstrated that both protein and gene levels of occludin and ZO-1 in the brain decreased apparently after two exposure days, suggesting that loss of tight junction associated proteins might occur at the early phase of 1,2-DCE- induced brain edema." (PMID 29410610, 2018). "Therefore, the aim of the present study was to investigate the relationships between the serum occludin level and the extent of PTBE before surgery and the extent of pericavity brain edema after surgery in patients with brain tumors." (PMID 32884584, 2020). "The accumulated results in our laboratory have demonstrated that up-regulated expression of MMP-9 and AQP4, and down-regulated expression of tight junction proteins, such as ZO-1 and occludin could be induced by 1,2-DCE poisoning during the course of brain edema." (PMID 29410610, 2018). "We obtained preliminary conclusions from serum indicators of clinical patients that miR-7-5p may affect brain edema, but it does not affect MMP-9, ZO-1, occludin, IL-6, TNF-α, NLR, and CRP expression to affect the formation of brain edema." (PMID 33392188, 2020).
E. coli infection (14 papers, 2014 to 2026). "Western blot analysis revealed that E. coli infection significantly reduced claudin‐1 and occludin protein levels in Caco‐2 cells compared to control cells, confirming the pathogen‐induced disruption of TJs." (PMID 41504183, 2026). "As expected, the F18+E. coli infection decreased the relative gene expression of tight junction proteins (OCLN and ZO-1) on day 7 post-challenge, although a recovery effect was observed on day 21 post-challenge." (PMID 39953722, 2025). "The results showed that E. coli infection impaired intestinal barrier function, manifested by downregulation of Occludin and Claudin-1 mRNA expression in the jejunum." (PMID 41463799, 2025). "Previous studies indicated that E. coli infection elevated the mRNA and protein levels of tight junction proteins ZO-1 and occludin." (PMID 34299517, 2021). "E. coli infection decreased the expression of ZO-1, occludin, and MUC2, while MPX treatment significantly increased their expression in the jejunum and colon; this effect of MPX was superior to that of Enro (p < 0.05)." (PMID 34177825, 2021). "We here report the importance of sufficient vitamin D levels to ensure enough high levels of the barrier proteins occludin and claudin-14 in the urinary bladder of postmenopausal women and in mice during E. coli infection." (PMID 31930458, 2020). "E. coli infection significantly decreased ZO-1, claudin-1 and occludin mRNA expression, as compared with their expression levels in the NC mice." (PMID 29402269, 2018). "Immunofluorescence microscopy revealed a redistribution of the tight junction proteins occludin and claudin-3 and increased expression of claudin-2 upon E. coli infection." (PMID 24637645, 2014). "A previous study in Holstein male calves found that Escherichia coli infection could down-regulate the gene expression of tight junction proteins, including claudin-1, occludin and and ZO-1." (PMID 39901713, 2025). "However, during E. coli infection, vitamin D induced occludin and claudin-14 in mature superficial umbrella cells of the urinary bladder, as demonstrated by immunohistochemistry." (PMID 31930458, 2020). "At the protein level, WB analysis consistently showed a significant downregulation in the expression of ZO-1, Occludin, and CLDN-3 following E. coli infection (p < 0.05)." (PMID 41302013, 2025). "Escherichia coli infection reduced the expression of ZO-1, occludin, and MUC2 in the mouse jejunum and colon, while the expression of ZO-1, occludin, and MUC2 was improved after treatment with MPX." (PMID 34177825, 2021).